ERN1 (endoplasmic reticulum to nucleus signaling 1)
Diseases named in the same sentence as ERN1 in open-access papers (continued):
Sharing a sentence is not in itself a finding about the gene and the disease.
infection (161 papers, 2008 to 2026). The state of being infected such as from the introduction of a foreign agent such as serum, vaccine, antigenic substance or organism. "Mutation of ERN1 often results in misshapen root hair tips, deficient infection thread formation, and immature root nodules." (PMID 36733592, 2022). "Both the NSP1-NSP2 complex and ERN1 transcription factors are essential for triggering the full-level expression of the Enod11 gene encoding proline-rich cell wall protein necessary for infection development." (PMID 35009060, 2021). "This work showed that Ern1, a transcription factor implicated in cytokinin signaling, has a less relevant role during intercellular infection by IRBG74." (PMID 33793909, 2021). "The bit1-1 mutation affects the ERN-1 transcription factor required for nodulation and the initiation of infection threads and the nsp2-2 mutation affecting a GRAS domain transcription factor, causes defects in infection and cortical cell division following inoculation with Sinorhizobium meliloti." (PMID 24015832, 2013). "Taken together, these analyses indicate that root hair infection chamber formation is sufficient in ern1 to trigger MtAnn1-GFP-labelled bridge in the root hair itself and adjacent cortex." (PMID 39638784, 2024). "The phenotype of ern1 mutants and expression pattern of ERN1 suggest that ERN1 is needed for infection thread formation and promote nodule organogenesis." (PMID 36733592, 2022). "Since the infection process is also controlled by several transcriptional regulators, the role of Nin, Cyclops, Ern1, Nsp1, and Nsp2 were tested with IRBG74." (PMID 33793909, 2021). "Inoculation of L. japonicus mutants shows that Ethylene-responsive factor required for nodulation 1 (Ern1) and Leu-rich Repeat Receptor-Like Kinase (RinRK1) are dispensable for intercellular infection in contrast to intracellular infection." (PMID 33793909, 2021). "Infection and nodulation induces the expression of ERN1 (ETHYLENE-RESPONSIVE BINDING DOMAIN FACTOR REQUIRED FOR NODULATION) and EARLY NODULATION 40 (ENOD40)." (PMID 28771548, 2017). "Overall, this suggests that NSP1/NSP2, NF-YA and ERN1 act in combination to regulate the expression of early infection markers, such as ENOD11 with the appropriate spatial and temporal patterns." (PMID 27586842, 2016). "NSP1 and NSP2 have been shown to dimerize and to bind a promoter region called the infection box in the MtEnod11 promoter, but also to activate the expression of ERN1, another TF involved in both rhizobial infection and nodule organogenesis." (PMID 24319255, 2014). "Compared with the drastic infection phenotypes of ern1, nsp1/2, and nin mutants, the infection phenotype of the Mtnf-ya1-1 mutants is less pronounced, as ITs occasionally reach the cortex in this mutant." (PMID 24319255, 2014). "We found that the expression of PB1-F2 during the infection represses the entire gene cluster representative of the two pathways with the exception of ERN1." (PMID 24959667, 2014). "Several nodulation-defective mutants have been identified in which infection pockets are initiated or established, but most infection thread growth is blocked; some of these mutations are in regulatory genes such as, NIN, LIN, RPG, ERN1 and NFYA1." (PMID 26517270, 2015). "The role that signaling pathways downstream of BRs play in symbiosis establishment was assessed by evaluating relative symbiosis-related (NIN1a, NSP1a, and ERN1) and defense-related (PR1, PR2, and PR5) gene expression 24 h after infection." (PMID 39886690, 2024). "In mice infected with ovalbumin-expressing Listeria monocytogenes (LM-OVA), both ERN1 (IRE1) and ATF6 mRNA were shown to increase 12 hours post-infection via a transcriptome analysis." (PMID 39026685, 2024). "This activation leads to the development of the infection program in epidermis cells, where the NIN, NF-YA1, and ERN1 transcription factors bind with a whole complex of additional regulators based on Chip-seq analysis." (PMID 35009060, 2021).
infection (continued). "The orthologs of ERN1, a transcriptional regulator of early nodulin ENOD1129, showed up-regulation in nod+ F487A upon infection." (PMID 28059169, 2017). "This suggests that ERN1 is not required to promote pre-infection priming, but in its absence the priming response is deregulated." (PMID 39638784, 2024). "However, a milder symbiotic perturbance was observed in the rbohE, rbohG, RPG, RPG-Like, RINRK1, ERN1, and VPY2 infection gene mutants in the intercellular interaction with IRBG74, compared to the phenotype observed with M. loti as the inoculum." (PMID 35812902, 2022). "As GAs inhibit the NF induction of the ENOD11 symbiotic infection marker, the expression of which directly depends on the previously identified NF signalling genes NSP1, NSP2 and ERN1 (refs 10, 11, 12, 13, 14), we then investigated if GAs could affect their expression." (PMID 27586842, 2016). "The absence of epidermal infection threads in Rl Norway-inoculated roots is supported by the reduced induction of NIN, ERN1, and EPR3 at 3 dpi." (PMID 30775775, 2019).
bacterial infections (11 papers, 2014 to 2022). "RPN5 RNAi and ERN1 RNAi blocked NF-ΚB activation in response to bacterial infection." (PMID 27819340, 2016). "In addition, MtNF-YA1 and MtNF-YA2 are required for bacterial infection and for the induction of early nodulation genes, such as ERN1 and ENOD11." (PMID 25642232, 2014).
ERN1 also shares sentences with these, for which no sentence is quoted: Hepatic steatosis (40 papers); hepatocellular carcinoma (35); Hyperglycemia (29); ovarian carcinoma (28); metabolic disorders (23); Sepsis (18); atherosclerosis (17); pulmonary fibrosis (16); type 2 diabetes (15); neurodegenerative disease (14); ZIKV infection (13); Parkinson disease (12); liver cancer (11); gastric cancer (10); rheumatoid arthritis (10); amyotrophic lateral sclerosis (9); heart failure (9); acute myeloid leukemia (8); inflammatory bowel disease (8); lupus (8); metabolic syndrome (8); non-small cell lung carcinoma (8); osteosarcoma (8); cardiac hypertrophy (7); Cerebral ischemia (7); diabetic nephropathy (7); endothelial dysfunction (7); Glucose intolerance (7); insulinoma (7); liver fibrosis (7).
A further 269 diseases each share a sentence with ERN1 in 7 papers or fewer.